CCL2 (C-C motif chemokine ligand 2)
Diseases named in the same sentence as CCL2 in open-access papers (continued):
Sharing a sentence is not in itself a finding about the gene and the disease.
atherosclerosis (continued). "CCL2 induces inflammation and monocyte recruitment in adipose tissue via its receptor CCR2, which is associated with the exacerbation of metabolic diseases such as atherosclerosis." (PMID 39334887, 2024). "In addition to atherosclerosis, studies highlight the role of CCL2 in age-related vascular changes that contribute to hypertension." (PMID 39201480, 2024). "Although these studies support a role of the CCL2/CCR2 axis in human atherosclerosis, it remains unclear whether pharmacological intervention in this pathway could lead to atheroprotection in humans." (PMID 37645892, 2024). "Alternatively, it may be the result of multiple opposite effects of SMC-derived CCL2 on atherosclerosis that outbalance each other." (PMID 38234375, 2024). "STAT4 absence could reduce the development of atherosclerosis by affecting MΦ activation and CCL2-induced MΦ migration." (PMID 36816804, 2023). "We next tested whether combined treatment with anti‐TNFα, anti‐CXCL2, and anti‐CCL2 would reduce the ability of aged fat transplants to enhance atherosclerosis." (PMID 36683460, 2023). "CCL2 may be involved in the recruitment of monocytes into the arterial wall during the progression of atherosclerosis." (PMID 38145212, 2023). "Finally, CCL2 has a vast literature supporting its role in inflammation and is also considered a target for atherosclerosis." (PMID 38031960, 2023). "Similarly, in atherosclerosis, monocyte chemoattractant protein-1 (CCL2) and oxidised low-density lipoproteins stimulate secretion of vimentin from macrophages." (PMID 35923851, 2022). "Furthermore, CCL2 seems to be an important chemokine in the development of atherosclerosis, since its expression has been detected in atherosclerotic lesions but not in vessels obtained from healthy individuals and in patients with MI." (PMID 35600479, 2022). "Moreover, sample size does not affect the major finding of this study, which is about the increased expression of YB1 phosphorylation in atherosclerosis and the related mechanism of CCL2 decay." (PMID 35990936, 2022). "Besides, our previous study demonstrated that Akt-specific inhibitor MK2206, a clinical phase II drug, showed an anti-atherosclerosis activity in vitro and in vivo, and it reduced plasma-CCL2 levels in ApoE−/− mice." (PMID 35990936, 2022). "Since the cholesterol efflux transporter ABCG1 also displays anti-inflammatory effects and CCL2 is an early component of the proinflammatory response in atherosclerosis, these data indicated that polarization with M-CSF induces proinflammatory traits in macrophages." (PMID 35237673, 2022). "Gene regulatory network analysis identified specific liver regulators related to lipid metabolism (SC5D, LCAT and HMGCR), inflammation (IL1A) and fibrosis (PDGF, COL3A1), linked to a set of aorta target genes related to vascular inflammation (TNFA) and atherosclerosis signaling (CCL2 and FDFT1)." (PMID 35897797, 2022). "Additionally, we found that inflammatory cytokines were downregulated in the presence of YB1 dephosphorylation, particularly CCL2, which participates in the pathogenesis of atherosclerosis." (PMID 35990936, 2022). "Using this method, we identified several hepatic regulators related to lipid metabolism (SC5D, LCAT and HMGCR), inflammation (IL1A) and fibrosis (PDGF and COL3A1) that were linked to a set of aorta target genes related to vascular inflammation (TNFA) and atherosclerosis signaling (CCL2 and FDFT1)." (PMID 35897797, 2022). "CCL2 seems to be involved in inflammation-driven angiogenesis and atherosclerosis." (PMID 36011581, 2022). "In contrast, lack of CCL2 decreased the atherosclerosis of low-density lipoprotein receptor-deficient mice." (PMID 36110847, 2022). "Moreover, the expression of Ccl2 has been found to increase in monocyte/macrophage from lesions of atherosclerosis and rheumatoid arthritis patients, indicating that Ccl2 is responsible for inflammatory cell infiltration and tissue destruction." (PMID 35548710, 2022).
atherosclerosis (continued). "Moreover, in autopsy-derived arterial specimens from patients, CCL2 was shown to be present in the early phases of atherosclerosis; the suggestion being that this chemokine contributes to the early influx of monocytes into the vessel wall." (PMID 34356595, 2021). "CCL2 promotes the recruitment of monocytes/macrophages into the intima and may be involved in regulating other signaling pathways related to atherosclerosis and metabolic disorders." (PMID 34777002, 2021). "Our study showed that benzoic acid could contribute to early atherosclerosis by inhibiting monocyte adhesion to the endothelium and abnormal CCL2 mRNA expression." (PMID 34679642, 2021). "There has been an intense focus on inflammation as an important driver of atherosclerosis in recent decades, and it has been demonstrated that knockout of certain chemokines, including monocyte chemoattractant protein-1 (MCP-1 or CCL2), reduces atherosclerosis." (PMID 34671275, 2021). "Plasma CCL2, also known as monocyte chemoattractant protein 1 (MCP-1), increases with lowering renal function, however, it appears to be an independent risk factor for death caused by other factors than atherosclerosis in patients with CKD." (PMID 33670423, 2021). "Besides this, it has been demonstrated that Bmal1 represses the expression of Ccl2; thus, myeloid-specific Bmal1 deletion increases monocyte recruitment and worsens atherosclerosis." (PMID 34447794, 2021). "CCL2 has been well characterised in atherosclerosis and arthritis development." (PMID 34492036, 2021). "It has been reported that targeting Ccl2 (C–C Motif Chemokine Ligand 2) could ameliorate atherosclerosis." (PMID 34130651, 2021). "Previous study has verified that elevated SASP mRNA expression (including Il-1α, Tnf-α, Ccl2, Mmp12, and Mmp13) significantly increases in senescent foamy macrophages during atherosclerosis, which has the similar characteristics of SASP in senescent macrophages during lung fibrosis." (PMID 34023858, 2021). "In another way, PCA has been shown to inhibit ICAM1 and vascular cell adhesion molecule 1 (VCAM-1)-dependent monocyte adhesion to activated HUVEC endothelium, as well as CCL2-mediated monocyte transmigration, thereby reducing the development of atherosclerosis in ApoE−/− mice." (PMID 32013236, 2020). "CCL2 was also reportedly involved in human atherosclerosis and myocardial infarction pathogenesis." (PMID 32257639, 2020). "That CCL2 and sCD163 were associated with atherosclerotic plaque at both coronary and carotid sites in this cohort of HIV-infected and uninfected men provides valuable evidence of its role in subclinical atherosclerosis." (PMID 30946765, 2019). "Increased interaction of various ligand-receptor pairs including Ccl2-Ccr2, Ccl7-Ccr2, and Il1b-Il1r2 between Mesen II and inflammatory cells in ApoE−/− adventitia further implied the participation of Mesen II in early development of atherosclerosis." (PMID 30943771, 2019). "C-C motif chemokine ligand 2 (CCL2) participates in the genesis and progress of atherosclerosis." (PMID 30961613, 2019). "The first chemokine implicated in atherosclerosis was CCL2, which is normally not found in the blood vessel wall, but is induced in the early phase of atherosclerosis." (PMID 30245686, 2018). "In an animal model ofatherosclerosis (cuff-induced accelerated atherosclerosis in ApoE3*Leidenmice) inhibition of QC activity reduced the number of adhering monocytes,down-regulated CCL2 in the media and the intima, and reduced neointima formation andlumen stenosis." (PMID 28739588, 2017). "Unlike CC-chemokine inhibitor 35K, the M3 protein is capable of sequestering members from all chemokine classes, specifically key chemokines involved in atherosclerosis progression including CCL2, CCL5 and CX3CL1, while displaying selectivity in its binding to individual members." (PMID 28282403, 2017).
atherosclerosis (continued). "Furthermore, levels of mRNA of several cytokines and other mediators of atherosclerosis were largely unchanged in mice treated with ampicillin, except for reductions in aortic Ccl2 and Icam1 mRNA levels." (PMID 26799618, 2016). "As vein graft lesions are highly enriched in SMC compared to atherosclerotic plaques, the effect of SMC derived products, such as CCL2, may be more prominent in vein graft disease as compared to atherosclerosis." (PMID 27053419, 2016). "CCL2 is likely to have considerable impact on PAD since the biological function of this chemokine is to induce monocyte migration and, as well, because the arteries with moderate atherosclerosis appear to accumulate CCL2 in response to a variety of pro-inflammatory stimuli." (PMID 25993297, 2015). "Moreover, the abundant expression and secretion of chitinase 3-like 1 (CHI3L1) at early stages of atherosclerosis triggers CCL2 expression in macrophages via activation of MAPK and NF-κB pathways." (PMID 26001902, 2015). "Moreover, blocking the interaction of miR-155 and its target Bcl6 maintains macrophage quiescence by suppressing CCL2 expression, which prevents the progression of atherosclerosis." (PMID 26001902, 2015). "On the other hand, selective CCL2 inhibition indicates a new approach for treating atherosclerosis." (PMID 25878716, 2015). "Among a number of genes already known to play major roles in the development of atherosclerosis such as Ccl2 (MCP-1), Rgs1 was identified as one of the novel candidate genes with higher expression in aortas from older ApoE−/− mice than in aortas from younger ApoE−/− mice." (PMID 25782711, 2015). "An A to G polymorphism in the CCL2 enhancer region at position –2578 (rs1024611; A>G), was found in most studies to be associated with higher serum CCL2 levels and increased susceptibility to a variety of diseases such as HIV-1 associated neurological disorders, tuberculosis, and atherosclerosis." (PMID 23166687, 2012). "In HIV-infected patients, genetic variations in the CCL2/CCR2 pathway have been associated with survival, and polymorphisms that increase the expression of CCL2 have been repeatedly associated with the presence of subclinical atherosclerosis." (PMID 22645407, 2012). "Targeting SELP and CCL2 may be a potential intervention for atherosclerosis therapy." (PMID 38794213, 2024). "Therefore, SELP and CCL2 were selected as the active targets for FDT against atherosclerosis." (PMID 38794213, 2024). "To our knowledge, it has not been tested whether the Ccl2-mCherry allele (without recombination) affects atherosclerosis, as we found for the floxed Ccl2 allele in the present study." (PMID 38234375, 2024). "Importantly, changes in plasma cholesterol and atherosclerosis remained in mice lacking Cre recombinase indicating that they were not caused by SMC-specific CCL2 deletion but by effects of the floxed allele or passenger genes." (PMID 38234375, 2024). "Accordingly, the critical role of CCR2/CCL2 in various inflammatory pathogeneses, including rheumatoid arthritis, asthma, multiple sclerosis, neuropathic pain, or atherosclerosis, has been largely documented and demonstrated in mice that are deficient for CCL2 or CCR2." (PMID 36729317, 2023). "CCL2 played a key role in amplifying and accelerating the inflammatory cascade and is closely related to chronic non‐controllable inflammation (cirrhosis, neuropathic pain, insulin resistance, atherosclerosis, deforming arthritis, ischemic injury, cancer, etc.)." (PMID 36872292, 2023). "Indeed, selective targeting of anti-inflammatory microRNAs to inflamed endothelium in a mouse model of atherosclerosis, lead to a local reduction in the expression of CCL2, among other chemokines, accompanied by reduced inflammation, macrophage numbers and plaque size." (PMID 35711383, 2022).
atherosclerosis (continued). "Interestingly, circulating CCL2 levels also correlate with subclinical atherosclerosis disease severity in postmenopausal women and may act as a potential early biomarker in this population." (PMID 35600479, 2022). "Monocyte chemotactic/chemo-attractant protein-1 (also known as C–C motif chemokine ligand 2, MCP-1/CCL2) is a key chemokine in the regulation of monocyte and macrophage migration and infiltration and has been associated with inflammatory diseases like atherosclerosis and rheumatoid arthritis." (PMID 34831917, 2021). "Both Ccr2 and Ccl2 knockout in atherosclerosis-prone mice as well as Ccr2 targeted siRNA treatment significantly reduced atherosclerotic plaque formation, whereas in contrast, leukocyte-specific overexpression of Ccl2 in Apoe−/− mice promoted atherosclerosis progression." (PMID 35087886, 2021). "In addition, the lncRNA CCL2 may contribute to human atherosclerosis via positively regulating CCL2 mRNA levels in endothelial cells." (PMID 33664877, 2021). "It has been shown that specific therapies targeting the pro/anti-inflammatory cytokines such as CCL2, TNFα, and IL-6 have suggested slowing in the progression of atherosclerosis in animal models and might improve cardiovascular outcomes in human subjects in large-scale phase III trials." (PMID 32821283, 2020). "In addition to greater levels of systemic inflammation, heightened monocyte activation (sCD163, CCL2) may contribute to the burden of atherosclerosis among HIV-infected persons." (PMID 30946765, 2019). "Additionally, CCL2 is absent in endothelium in normal conditions but is increased in the setting of atherosclerosis and associated with elevated risk of myocardial infarction." (PMID 28323859, 2017). "CCL2 and CCL5 are primarily involved in monocyte and SMC recruitment, promoting the formation of atherosclerosis, whereas CCL19 and CCL21 facilitate macrophage emigration, thereby promoting the regression of advanced plaques." (PMID 40236901, 2025). "In a mouse model of atherosclerosis, LRP1 was shown to inhibit the expression of inflammatory mediators such as CCL2 and MMP-9." (PMID 40564911, 2025). "Deleting CCL2 or CCR2 in murine models reduced atherosclerotic development and diminished macrophage deposit within plaques, while overexpression of CCL2 enhanced atherosclerosis." (PMID 38892201, 2024). "In cultured HAECs, we demonstrate that Oxy210 can inhibit the high baseline and TGF-β-induced expression of CCL-2 and MMP2, further supporting its potential utility in the context of vascular inflammation and atherosclerosis." (PMID 39404395, 2024). "In aged mice with atherosclerosis, TGF-β1 upregulates NOX4, which in turn activates CCL2 expression in VSMCs, further linking aging to increased CCL2 expression and inflammation related to atherosclerosis." (PMID 39201480, 2024). "In cardiovascular conditions, CCL2 and CCR2 are integral to atherosclerosis, myocardial infarction, and heart failure." (PMID 39201480, 2024). "When there is vascular injury or inflammation, such as in atherosclerosis or other inflammatory conditions as, for example, SLE, ECs lining the blood vessels can produce CCL2." (PMID 39242108, 2024). "The expression patterns of the major migration-driving chemokines MCP-1 (CCL2), MIP-1α (CCL3), MIP-1β (CCL4), RANTES (CCL5), and fractalkine (CX3CL1) in patients with atherosclerosis were of particular interest in this study." (PMID 38256102, 2024). "This activates M1-type macrophages which produce chemokines, namely CCL2, IL6, CXCL8, CXCL2, and CXCL20, leading to a complex cascade that encourages atherosclerosis." (PMID 39634983, 2024). "Our results were verified by qPCR for the selected cytokines involved in immune cell activation and migration (CCL2, CCL3, CCL4, CCL5, CX3CL1), representing potential therapeutic targets in atherosclerosis." (PMID 38256102, 2024).
atherosclerosis (continued). "Activation of this axis determined the significant down-regulation of downstream inflammatory cytokine MCP1 (CCL2 and CCL12), thereby reduced the inflammation, atherosclerosis and thrombogenesis effects at the systems-level." (PMID 37033947, 2023). "Epidemiological and laboratory evidence suggested the correlation and therapeutic potential of CCL2/CCR2 with the pathogenesis of atherosclerosis, and there is increasing evidence that lncRNAs are misregulated in atherosclerosis." (PMID 36872292, 2023). "Genes MSR1, CCL2, and CXCL known to be involved in the development of atherosclerosis through the activation of LXR/RXR and PPARα were upregulated." (PMID 36831031, 2023). "There is powerful proof that chemokine CCL2 and its receptor CCR2 function in cardiovascular diseases such as heart failure, atherosclerosis and coronary atherosclerotic heart disease, hypertension and cardiomyopathy." (PMID 36110847, 2022). "Previous studies have shown that CCL2 inhibition alone or in combination with CX3CR1 and CCR5 leads to decreased monocyte recruitment and thus inhibits atherosclerosis occurrence." (PMID 35509837, 2022). "Chemokines such as CCL2, CCL5, and CXCL10 play a crucial role in the early stages of atherosclerosis via EBD as well as via atherogenic phenotype switching of VSMCs." (PMID 36497143, 2022). "Based on the correlation criteria and correlation criteria value, CCL2, CCL4, TLR2, IL1B and PTPRC were identified as hub immune genes in atherosclerosis." (PMID 35509837, 2022). "Many studies in both humans and animals have shown the importance of MC chemoattractant protein-1 (MCP-1, also named CCL2) and its receptor CCR2 in pathologies, such as atherosclerosis." (PMID 34987524, 2021). "Another mouse model using APOE∗3-Leiden mice with alternating light/dark cycles also exhibited more severe atherosclerosis with more macrophages in the lesion due to increased expression of ICAM-1 and CCL2 in the lesions." (PMID 34557221, 2021). "The first molecule that has been investigated in atherosclerosis pathogenesis is chemokine ligand 2 (CCL2), also known as monocyte chemoattractant protein-1 (MCP-1), and it works with receptor chemokine receptor type 2 (CCR2)." (PMID 34345249, 2021). "These EOs are potentially useful in the management of inflammatory diseases mediated by CCL2 and TNF‐α, such as atherosclerosis and arthritis." (PMID 33379375, 2020). "Together, these findings strongly indicate that galectin-3 acts as a negative regulator of inflammation by modulating TGFβ signaling and reducing the expression of the proinflammatory molecules MMP12, CCL2, and PTGS2 in a mouse model of atherosclerosis." (PMID 32295421, 2020). "Of the many chemokines and cytokines that exist, five (IL-1, IL-6, TNF-α, IL-8, and CCL2/MCP-1) are involved in diseases such as psoriasis, rheumatoid arthritis, and atherosclerosis." (PMID 34211530, 2020). "Interestingly, deletion of both CCL2 and CX3CR1, or CCR2 and CX3CL1 even further decreased atherosclerosis development compared with single deficiencies in the proteins, which could be attributed to a strongly attenuated monocytosis and hence reduced plaque macrophage accumulation." (PMID 31191301, 2019). "Indeed, some authors showed that some cell types like vascular smooth muscular cells enhanced their CCL2 expression with aging, creating a sort of proinflammatory phenotype, leading both to chronic inflammation and arterial aging, and could enhance atherosclerosis." (PMID 29898739, 2018). "To confirm the induction of inflammation in irradiated TICAE cells, we focused on two pro-inflammatory cytokines involved in atherosclerosis: IL6 and CCL2." (PMID 28487652, 2017). "Various chemokines including CCL2 and CCL5 were shown to control the recruitment of myeloid cells to the aortas during atherosclerosis progression." (PMID 28536468, 2017).